TTN (titin)
Diseases named in the same sentence as TTN in open-access papers (continued):
Sharing a sentence is not in itself a finding about the gene and the disease.
congenital myopathy (14 papers, 2013 to 2025). "To date, all pathogenic TTN variants that have been described as associated with early-onset or congenital myopathies show recessive inheritance." (PMID 39684706, 2024). "Congenital titinopathies are an emerging group of a potentially severe form of congenital myopathies caused by biallelic mutations in titin, encoding the largest existing human protein involved in the formation and stability of sarcomeres." (PMID 36945066, 2023). "Congenital titinopathies are an emerging group of a potentially severe form of congenital myopathy caused by biallelic mutations in titin (TTN)." (PMID 36945066, 2023). "Thus, mutations in MTT-only exons could disrupt titin’s elasticity, resulting in skeletal muscle defects in muscle development that manifest as congenital myopathies such as arthrogryposis." (PMID 39684706, 2024). "In the congenital myopathy subgroup, 12 of 22 patients (54.5%) had disease-causing variants in RYR1 (n = 4), MYH7 (n = 3), TTN (n = 2), FHL1 (n = 1), NEB (n = 1), and SELENON (n = 1)." (PMID 40494860, 2025). "She wrote that central nuclei and small slow fibers seemed to be the main features, so a panel of congenital myopathy including MTM1, Titin (TTN), and RYR1 genes must be evaluated." (PMID 33432556, 2022). "Seven patients had congenital muscular dystrophies: LAMA2-related dystrophy (n = 5), COL6-related dystrophies (n = 1) or α-dystroglycanopathy (n = 1), and three patients had congenital myopathies: DNM2-related myopathy (n = 1) and TTN-related myopathy (n = 2)." (PMID 32028919, 2020).
muscle disorders (14 papers, 2014 to 2025). "Mutations in titin and their underlying mechanisms have yet to be fully elucidated and are critical for understanding titin’s contribution to muscular diseases and physiological function." (PMID 39737810, 2025). "Mutations in the gene encoding the giant skeletal muscle protein titin (TTN) were reported that associated with several muscle disorders and were frequently detected in solid tumors." (PMID 35402275, 2022). "Mutations in TTN are typically linked to heart and muscle disorders." (PMID 40649942, 2025). "Titin is a key muscle-associated protein linked to various muscular diseases, including dystrophy." (PMID 41488750, 2025). "TTN mutations can cause a wide spectrum of muscle disorders called titinopathies." (PMID 37497165, 2023). "Titinopathies are inherited muscular diseases triggered by genetic mutations in the titin gene." (PMID 36115951, 2022). "One such example is titin (TTN), a giant filamentous protein expressed in the muscles of all bilaterian metazoans that plays a key role in muscle elasticity and is linked to various human muscular diseases." (PMID 30804022, 2019). "Titin, a component protein of the sarcomeres of striated muscles, has recently been attracting increasing attention as a new marker of muscle disorders, and measurements of the urinary excretion of the N-terminal fragment of titin (N-titin) have been established." (PMID 33802012, 2021). "TCAP encoded telethonin is a 19 kDa protein, which plays an important role in anchoring titin in Z disc of the sarcomere, and is known to cause LGMD2G, a rare muscle disorder characterised by proximal and distal lower limb weakness, calf hypertrophy and loss of ambulation." (PMID 25055047, 2014).
Skeletal myopathy (14 papers, 2013 to 2026). "Following introduction of next generation sequencing into routine clinical diagnostics, TTN variants are increasingly identified in patients presenting with primary skeletal myopathies." (PMID 33449170, 2021). "TTN encodes the large sarcomeric protein titin, and TTN mutations have been implicated in cardiac and skeletal myopathies." (PMID 23476865, 2013). "We propose that digenic inheritance of deleterious changes impacting both the protein kinase SRPK3 and the giant muscle protein titin causes a skeletal myopathy and might serve as a model for other genetic diseases." (PMID 38429495, 2024). "TTN-related known skeletal muscle disorders follow the autosomal-dominant pattern of inheritance, which is a common characteristic of distal arthrogryposes as well." (PMID 35951140, 2022). "The TTN deletion was shown to segregate with a skeletal myopathy phenotype in two additional family members." (PMID 31489791, 2019). "Several TTN‐related skeletal myopathies are currently known." (PMID 31489791, 2019). "Mutations in the TTN gene cause several different and heterogeneous skeletal muscle disorders with or without cardiac involvement, characterized by a variability in the age of onset, muscle involvement, and disease-course." (PMID 29598826, 2018). "Hence, these chaperones were considered unlikely to cause the rise in titin-based PT in skeletal myopathies and not studied further." (PMID 28915917, 2017). "To achieve a comprehensive view of titin ASEs in adult human skeletal muscles, we performed a RNA-Sequencing experiment on 42 human biopsies collected from 12 anatomically different skeletal muscles of 11 individuals without any skeletal-muscle disorders." (PMID 29598826, 2018).
Myocardial fibrosis (13 papers, 2019 to 2025). "Moreover, in the same study, the authors studied the variant in heterozygosis, which was associated with ventricular dilatation and upregulation of the wild-type titin allele, leading to diffuse myocardial fibrosis under angiotensin II exposure." (PMID 41465321, 2025). "Beside titin modifications and myocardial fibrosis, altered diastolic Ca2+ hemostasis is a key factor in development and progression of diastolic chamber stiffness and diastolic dysfunction." (PMID 39355352, 2024). "Reduced left ventricular compliance and relaxation are mainly due to myocardial fibrosis and increased myocardial stiffness induced titin post-translational modifications." (PMID 34299270, 2021). "Many histopathological mechanisms are the substrates of left ventricle stiffness, such as myocardial fibrosis, titin and other sarcomeric proteins alterations, sarcoplasmic calcium reuptake imbalance and cytoskeleton alterations during protodiastole." (PMID 34299270, 2021). "Our findings were accompanied by reduced myocardial fibrosis and restored titin phosphorylation, both indicating preserved left ventricular elasticity." (PMID 33808232, 2021). "Myocardial stiffness is strongly determined by alterations in the extracellular matrix, such as myocardial fibrosis, and by changes in cardiomyocyte myofilamentary proteins, mainly titin, a major contributor to cardiomyocyte passive tension." (PMID 30814653, 2019). "This change in Titin is in response to pressure overload and might further promote myocardial fibrosis or severe aortic stenosis." (PMID 36071494, 2022). "Intriguingly, however, and in contrast to moderate exercise, intense exercise could not reverse the obesity-induced titin isoform imbalance or blunt myocardial fibrosis." (PMID 37508000, 2023). "Furthermore, molecular pathways independent of titin compliance including myocardial fibrosis and calcium handling may contribute to LV diastolic dysfunction in this study." (PMID 36494772, 2022).
diabetes (10 papers, 2015 to 2025). "Titin+ patients had increased risk of hypertension [OR = 2.358 (95% CI 1.606, 3.463)], diabetes [OR = 1.882 (95% CI 1.171, 3.026)], cardiovascular and cerebrovascular diseases [OR = 1.976 (95% CI 1.173, 3.330)], and eye diseases [OR = 3.800 (95% CI 1.573, 9.181)]." (PMID 39968461, 2025). "A recent study showed how treatment with Neuregulin1 (NRG-1) was able to rescue titin-based cardiomyocyte stiffening in diabetic mouse hearts, via increased PKG and ERK1/2 activity and reduced PKCα activity, which reversed the changes in titin-phosphorylation associated with diabetes." (PMID 30425649, 2018). "In addition, ML models have been applied to integrate genetics, cardiac imaging, biobank data, and clinical information from EHRs for high-throughput mapping of genotype–phenotype associations to predict diabetes, titin-truncating variants related to DCM, and CAD." (PMID 35207566, 2022). "This includes age, sex, diabetes, kidney disease, inflammation, and mutations in sarcomeric proteins such as titin and splice factors such as RBM20, a regulator of titin based stiffness." (PMID 29889873, 2018). "First, previous reports demonstrated that 20 weeks of STZ-induced diabetes in rats led to a shift to a more compliant isoform of titin, a sarcomeric protein involved in myocardial stiffness." (PMID 26901278, 2016). "A diabetes-specific targeted analysis showed negatively enriched Z-disc and contractile gene sets enriched due to the downregulation of CASQ2, peripherin (PRPH), nebulette (NEBL), titin-cap (TCAP), and LIM domain-binding proteins LDB3, PDLIM4, and PDLIM5 (Dataset EV36)." (PMID 40759793, 2025). "This is not to say that the ROCK mediated reduction in MyBP-C phosphorylation activity does not become more pronounced in advanced diabetes, but rather other accessory proteins may be more important in modulating myosin head extension in early diabetes, such as titin." (PMID 26194354, 2015).
Duchenne muscular dystrophy (10 papers, 2016 to 2025). Duchenne muscular dystrophy (DMD) is a neuromuscular disease characterized by rapidly progressive muscle weakness and wasting due to degeneration of skeletal, smooth and cardiac muscle. "Despite the fact that changes in the expression profile of titin were analyzed above all in the context of muscular metabolism, including Duchenne muscular dystrophy, the connection of this protein with carcinogenesis has been studied recently." (PMID 38275878, 2024). "A total of 15,318 circRNAs have been identified in the human heart, and highly expressed circRNA correspond to key cardiac genes, including titin, ryanodine receptor 2, and Duchenne muscular dystrophy." (PMID 31991759, 2020). "It has been shown before by qPCR that many “DM1-specific” splice events are shared between DM1 and Duchenne muscular dystrophy (DMD) including, among others, MBNL1, ATP2A1, TTN, TNNT2 and MEF2A/C." (PMID 40149583, 2025).
limb-girdle muscular dystrophy (10 papers, 2012 to 2025). Limb-girdle muscular dystrophy (LGMD) is a heterogeneous group of muscular dystrophies characterized by proximal weakness affecting the pelvic and shoulder girdles. "The combined recessively/dominantly transmitted c.19993G>T and c.107545delG mutations in TTN gene cause a limb girdle muscular dystrophy phenotype with the classical myofibrillar myopathy histological changes." (PMID 33041974, 2020). "Limb-girdle muscular dystrophy (LGMD) is a progressive muscle weakness affecting the pelvic and shoulder girdles, primarily caused by mutations in proteins like myotilin, lamin, caveolin-3, calpain-3, dysferlin, γ-sarcoglycan, TCAP, TRIM32, FKRP, and titin." (PMID 39415830, 2024).
lung squamous cell carcinoma (10 papers, 2020 to 2024). "In our study, it was found that the prolonged survival of lung squamous cell carcinoma patients was caused by TTN mutation." (PMID 37035196, 2023). "TTN is a frequently mutated gene in lung squamous cell carcinoma, and autoantibodies against titin are identified in patients with the autoimmune disease scleroderma." (PMID 34746153, 2021). "In conclusion, this work demonstrated that mutated TTN was frequently identified in lung squamous cell carcinoma, and mutated TTN was related to higher TMB and indicated prognostic result." (PMID 34746153, 2021). "TTN deletion mutation has a positive prognosis for lung squamous cell carcinoma but has nothing to do with lung adenocarcinoma." (PMID 32670437, 2020). "Missense mutations in TTN has been reported in lung squamous cell carcinoma and has been shown to promote their growth." (PMID 32626534, 2020). "Studies have reported that TTN missense mutations are correlated with lung squamous cell carcinoma." (PMID 35766333, 2022). "Besides, TTN is also frequently mutated in a variety of cancers, including lung squamous cell carcinoma, LUAD and colon adenocarcinoma." (PMID 35614936, 2022). "Even if TTN is also frequently mutated in Chinese lung squamous cell carcinoma samples, the effect may be somewhat heterogeneous between different ethnic groups." (PMID 34746153, 2021). "Based on this finding, we aimed to further identify whether TTN mutation is the independent prognostic factor for lung squamous cell carcinoma using Cox regression analysis." (PMID 34746153, 2021). "Therefore, our results reveal that mutated TTN might be a convenient prediction for ICB immune treatment in lung squamous cell carcinoma patients." (PMID 34746153, 2021). "Hence, we speculated that TTN mutation with a high TMB in lung squamous cell carcinoma might drive the immune system to fight against tumor cells." (PMID 34746153, 2021). "Eighty-five percent of lung squamous cell carcinoma patients with TTN mutant type had missense variations and favorable overall survival." (PMID 34901000, 2021). "In a retrospective study analyzing somatic mutations in 480 patients with lung squamous cell carcinomas, patients with TTN mutations had a better prognosis than patients without TTN mutations." (PMID 39240165, 2024). "Consequently, the relationship between mutant TTN and prognostic results, such as immunocyte infiltration and signaling pathways, demands more verification in lung squamous cell carcinoma specimens from China." (PMID 34746153, 2021). "However, the changes in TTN mutations and their relationship with TMB and immunocyte-infiltrating cancers in lung squamous cell carcinoma remain vague." (PMID 34746153, 2021). "Therefore, we assumed that TTN mutation might positively regulate macrophages M1, CD4, and CD8 T cells in lung squamous cell carcinoma." (PMID 34746153, 2021).
Ventricular arrhythmia (10 papers, 2018 to 2025). "Since patients with titin CMP are at risk of developing ventricular arrhythmias and thus to experience sudden cardiac death, appropriate anti-arrhythmic therapy needs to be established." (PMID 30061524, 2018). "For instance, the most common genetic cause of DCM, truncating titin (TTN) variants, lead to pronounced mitochondrial dysfunction with increased ventricular arrhythmias, which are the lethal causes of DCM." (PMID 35571180, 2022). "The two patients with TTN pathogenic variants presented no sign of structural heart abnormalities, and we found no higher prevalence of ventricular arrhythmias in the patients with P/LP in SCN5A." (PMID 40067976, 2025).
Hypertension (9 papers, 2017 to 2025). The presence of chronic increased pressure in the systemic arterial system. "Collectively, these results indicate that titin‐based alterations in VSMC tone impact arterial stiffness in the context of Ang II‐associated hypertension." (PMID 40119572, 2025). "We further show that the expression of a larger titin isoform ameliorates cardiac remodeling caused by Ang II‐associated hypertension." (PMID 40119572, 2025). "In our cohort, sex, hypertension, and the presence of a truncating variant in the titin gene were associated with LV mass." (PMID 35027315, 2022). "Furthermore, our data provide proof‐of‐concept evidence that targeting RBM20 to reduce arterial stiffness through titin isoform switching may benefit aging‐ or hypertension‐associated arterial stiffness and vascular diseases." (PMID 40119572, 2025). "Our findings suggest that a similar strategy targeting the RBM20‐titin axis to fine‐tune VSMC stiffness could alleviate hemodynamic stress on the heart and lower the risk of end‐organ damage in the context of hypertension." (PMID 40119572, 2025). "We are the first to hypothesize a role of increased Titin in hypertension in relation to preeclampsia." (PMID 29093568, 2017). "Our aim is to compare a metabolic syndrome- (ZSF-1 rats) and a hypertension-driven (Dahl salt-sensitive (DSS) rats) HFpEF rat-model in relation to SKM function and titin phosphorylation." (PMID 40649974, 2025). "Future studies will be necessary to establish the specific role that decreased titin‐based VSMC and arterial stiffness play in cardiac remodeling secondary to hypertension." (PMID 40119572, 2025). "Larger titin in smooth muscle reduced the stiffness of isolated VSMCs, as well as arterial stiffness in the context of Ang II‐induced hypertension but not at baseline." (PMID 40119572, 2025).
myofibrillar myopathy (9 papers, 2017 to 2025). "Moreover, in adults, where muscle weakness is not pronounced, the differential diagnosis includes conditions such as hereditary myopathy with early respiratory failure (HMERF) due to TTN variants and myofibrillar myopathies." (PMID 39468638, 2024). "Truncating variants in TTN are strongly associated with DCM, while mutations in DSP, LMNA, MYH7, RBM20, TNNT2, BAG3, and FLNC (the latter being linked to myofibrillar myopathy) are also commonly implicated." (PMID 39857686, 2025). "While TTN is a known causative gene for myofibrillar myopathy, the missense VUS identified in this case do not meet the criteria for a (likely) pathogenic variant based on current ACMG guidelines." (PMID 40606663, 2025).
bladder cancer (8 papers, 2020 to 2023). "Compared to the ATM-WT group, ARID1A and TTN mutations were significantly upregulated in the ATM-MT group in the immunotherapy cohort and the TCGA-Bladder cancer cohort, respectively." (PMID 32922441, 2020). "The results showed that TJP1 mRNA levels were positively correlated with TTN and RYR3 mRNA levels in bladder cancer tissues." (PMID 35087173, 2022). "TJP1 mRNA levels were positively correlated with TTN and RYR3 mRNA levels in bladder cancer tissue." (PMID 35087173, 2022).
distal myopathy (8 papers, 2015 to 2024). Distal myopathy refers to a group of muscle diseases which share the clinical pattern of predominant weakness and atrophy beginning in the feet and/or hands. "TTN variations cause muscle-related ailments like Myopathic congenital arthrogryposis, distal myopathies, and other forms of myopathies." (PMID 35061126, 2022). "TTN was also listed in massively parallel sequencing in an attempt to spot rare variants of genes causing distal myopathy, cardiac muscle, and skeletal muscle diseases." (PMID 35061126, 2022).